ARID1A (AT-rich interaction domain 1A)
Diseases named in the same sentence as ARID1A in open-access papers (continued):
Sharing a sentence is not in itself a finding about the gene and the disease.
lung adenocarcinoma (17 papers, 2017 to 2026). A carcinoma that arises from the lung and is characterized by the presence of malignant glandular epithelial cells. "In a Spanish cohort of 185 treatment-naïve patients, 12% of advanced lung adenocarcinoma cell-free DeoxyriboNucleic Acid (cfDNA) samples analyzed with Guardant360 harbored ARID1A mutations (61% pathogenic/likely pathogenic)." (PMID 33608032, 2021). "To date, no clear epidemiological, clinicopathological, or molecular features have been specifically related to lung adenocarcinoma with ARID1A mutations." (PMID 33608032, 2021). "An 8% prevalence of ARID1A gene mutations has been described with next-generation sequencing (NGS) in lung adenocarcinoma samples." (PMID 33608032, 2021). "Knockdown of ARID1A in lung adenocarcinoma cell lines promoted cell proliferation, migration, invasion, and enhanced phosphorylation of Akt, and there are enhanced tumour metastases in xenograft models." (PMID 38275587, 2023). "Dysregulated ARID1A expression is frequently detected in lung adenocarcinoma (LUAD) and mediates significant changes in cancer behaviors and a poor prognosis." (PMID 36869329, 2023). "This is the first case report in lung adenocarcinoma of ARID1A gene alterations leading to sporadic MSI, through somatic mutL homolog 1 (MLH1) promoter methylation, with an MLH1 gene mutation as the second somatic hit." (PMID 33608032, 2021). "For this, we made use of a GR activity score (explained above) and the lung adenocarcinoma dataset from TCGA (91/877 tumours harboured SWI/SNF mutations; SMARCB1 18.09%; SMARCC2 9.52%, SMARCD2 6.66%, SMARCD3 1.90%, ARID1A 29.52%, ARID2 31.42%, SMARCE1 2.85%)." (PMID 34272384, 2021). "It is our opinion that ARID1A gene should be included in comprehensive NGS molecular platforms used in advanced lung adenocarcinoma." (PMID 33608032, 2021). "MiR-769-5p was found upregulated in hypoxia-induced human lung adenocarcinoma cells, affecting the cell cycle of A549 cells, while its predicted target genes, including ARID1A and SMAD2, were downregulated." (PMID 33329055, 2020). "This is the first case report in lung adenocarcinoma of ARID1A gene alterations leading to sporadic MSI, through somatic MLH1 promoter methylation, with an MLH1 gene mutation as the second somatic hit, showing a clinical and radiologic response to an immune checkpoint inhibitor." (PMID 33608032, 2021). "ARID1A or ARID1B expression was related to immunosuppression in 517 lung adenocarcinoma (LUAD) samples and 501 lung squamous cell carcinoma (LUSC) samples, which is mainly characterized by significant reductions in the abundances of activated CD8+ T cells and activated dendritic cells (DCs)." (PMID 32791957, 2020). "In this particular case, we show that ARID1A gene mutations with sporadic MSI due to somatic MLH1 gene promoter methylation and MLH1 gene mutation could change the prognosis and define the response to immunotherapy in a patient with lung adenocarcinoma." (PMID 33608032, 2021). "Compared to lung adenocarcinoma (LUAD) cell lines, SCLC cell lines display markedly higher ARID1A expression." (PMID 41049615, 2025). "A change in correlation may be coincident with differentialexpression for some genes, as seen in ARID1A in lung adenocarcinoma(middle row).However, a change in correlation is not synonymous with differentialexpression." (PMID 40674356, 2025).
meningioma (17 papers, 2017 to 2026). A generally slow growing tumor attached to the dura mater. "ARID1A mutations occurred with similar frequency in both low- and high-grade meningiomas; however, mutations in ARID1A were found to be an independent poor prognostic indicator with a 7.421-fold increased hazard of death (p = 0.04)." (PMID 37173979, 2023). "In the cohort of only CDKN2A intact/wt meningiomas, all meningiomas with PIK3CA or POLR2A mutations were CDKN2Alow cases, whereas the only meningioma with an ARID1A mutation was CDKN2Ahigh." (PMID 37093270, 2023). "If mutations in ARID1A are present in the primary tumor such as atypical meningiomas, these tumors tend to have a worse prognosis." (PMID 37711591, 2023). "Among the NF2-mutated meningiomas, two cases, resected from male patients and located at the convexity, showed 1p and/or 22q deletion, and ARID1A or FBXW7 mutation." (PMID 33670055, 2021). "Genetic alterations involving several other subunits of the SWI/SNF complex (in particular SMARCB1 and ARID1A) are found in meningioma pathogenesis and seem to be associated with more aggressive subtypes of meningioma." (PMID 33319313, 2021). "An interesting finding was that the fastest growing cranial meningioma (P6_C1) carried one-copy loss of ARID1A and SMARCE1, the subunits of SWI/SNF, and one-copy gain of SUZ12 and EZH1, the components of PRC2." (PMID 32724039, 2020). "Other mutations associated with meningiomas (ARID1A, SMO and TRAF7) were also restricted to sporadic meningiomas, suggesting that radiation therapy induces tumorigenesis through a different set of genetic alterations to those of sporadic meningioma." (PMID 28775249, 2017). "In a case study of an untreated, rare intraventricular meningioma, whole-exome sequencing data revealed the presence of an ARID1A frameshift deletion in grade 2 and grade 3 sections of the tumor." (PMID 37173979, 2023). "In another study of 255 meningiomas, including 63 WHO grade 1, 173 grade 2, and 19 grade 3 meningiomas, the authors found ARID1A, SMARCA4, and SMARCB1 mutations in 17.3, 3.5, and 5.1% of samples, respectively." (PMID 37173979, 2023). "A history of meningioma recurrence/progression and deletions of chromosome 1p (chr1p/chr1p36 alterations or ARID1A alterations, P < 10) were significant drivers of the second principal component." (PMID 35769412, 2022). "Additional mutations have been described, including ARID1A and SMARCA4, with ARID1A mutations being present in ~ 20% of grade I and II tumors, 15% of grade III meningiomas, and associated with increased mortality." (PMID 34846640, 2022). "ARID1A alterations were significantly more common in WHO grade 3 meningiomas (n = 26/176, 14.8%) than in WHO grade 2 (n = 18/441, 4.1%, p = 0.0001) and WHO grade 1 meningiomas (n = 1/220, 0.4%, p = 0.0001)." (PMID 33087175, 2020). "Other common driver mutations in our cohort such as CDKN2A, ARID1A, BRCA1, NF1, AKT1, SMO, PIK3CA have similarly been noted in various prior sequencing studies of meningiomas." (PMID 31191822, 2019). "Furthermore, were observed a significant association of alterations in the chromatin regulator ARID1A in NF2-mutant meningiomas (n = 34/472, 7%) versus NF2-wt meningiomas (n = 12/377, 3.2%, p = 0.0138)." (PMID 33087175, 2020). "We also observed an enrichment in alterations in CDKN2A/B, KDM6A, ARID1A, PTEN, FBXW7, and SUFU in comparison with NF2-wt meningiomas." (PMID 33087175, 2020). "CDKN2A, ARID1A, BRCA1, NF1, and AKT1 were also commonly identified in meningioma samples across the cohort." (PMID 31191822, 2019).
metastatic tumors (17 papers, 2015 to 2025). "Using a forward-mutagenesis Sleeping Beauty (SB) transposon-based screen in a Probasin Cre-Recombinase (Pb-Cre) Pten-deficient mouse model of PC, we identified Arid1a loss as a driver in the development of metastatic disease." (PMID 39885328, 2025). "The mechanisms of why KRASG12D is associated with poor prognosis relative to the other subtypes is not fully understood beyond the co-mutation with ARID1A and enrichment in metastatic disease." (PMID 38310130, 2024). "It has been proven that ARID1A plays an important role in chromatin reprogramming, and inactivated ARID1A mutations occur more frequently in metastatic tumors and tumors with hormone therapy progression." (PMID 38365747, 2024). "Apart from ARID1A and KMT2C, ZFHX3 and NF1 are also associated with endocrine resistance in metastatic disease." (PMID 39594781, 2024). "The proportion of metastatic tumors in the Arid1a wildtype mice with a primary tumor was 0% (n = 86); for the Arid1a homozygous KO mice, it was 41% (n = 41); and for the heterozygous KO mice, it was 55% (n = 20)." (PMID 39123453, 2024). "The loss of the chromosome arm 1p in six patients with metastatic disease (GIST_124, _131,_178,_150, _174, _188) led also to one copy deletion of KIF1B and of the tumor suppressor ARID1A, a known SWI/SNF chromatin remodeling gene." (PMID 26544626, 2015). "However, mutations in genes such as BRCA2, ARID1A and KMT2C were reported only in metastatic tumors, implying evidence of their contribution to disease progression." (PMID 39594781, 2024). "Nevertheless, the fact that ARID1A was significantly elevated in primary tumours yet not in metastatic tumours among certain HCC patients suggests that ARID1A might be depleted upon onset." (PMID 39471843, 2024).
non-small cell lung carcinoma (17 papers, 2018 to 2024). A group of at least three distinct histological types of lung cancer, including non-small cell squamous cell carcinoma, adenocarcinoma, and large cell carcinoma. "ARID1A mutations were present in 6–11.3% of non-small-cell lung carcinomas (NSCLC), of which the majority (44–69%) were loss of function mutations, while less than 2% showed diffuse loss of expression." (PMID 38275587, 2023). "Genomic studies have identified frequent mutations in subunits of the SWI/SNF chromatin remodeling complex including SMARCA4 and ARID1A in non-small cell lung cancer." (PMID 39345502, 2024). "Loss of ARID1A, a subunit of the SWI/SNF chromatin remodeling complex, contributes to malignant progression in multiple cancers including non-small cell lung cancer (NSCLC)." (PMID 38229120, 2024). "Knockdown of ARID1A in non-small cell lung cancer (NSCLC) resulted in up-regulation of the expression of cycle-related proteins cyclinD1 and Bcl-2 and inhibition of apoptosis." (PMID 39697230, 2024). "On the other hand, knockdown of ARID1A upregulates the expression of cycle-related proteins cyclinD1 and Bcl-2 and inhibits cell apoptosis in non-small cell lung cancer (NSCLC)." (PMID 34671561, 2021). "In non-small cell lung cancer (NSCLC), the incidence of ARID1A mutation is only a few percent." (PMID 34065983, 2021).
prostate carcinoma (17 papers, 2015 to 2025). A carcinoma that arises from epithelial cells of the prostate gland. "Perhaps the most important differential diagnosis is sarcomatoid carcinoma of the prostate, and ARID1A mutations have rarely been documented in prostate carcinomas." (PMID 35125107, 2022). "ARID1A deletion induces the chemotaxis of polymorphonuclear bone marrow–derived suppressor cells, the main type of invasive immune cell that causes immune evasion, and promotes the progression of prostate cancer." (PMID 37215130, 2023). "Besides T cells, polymorphonuclear myeloid-derived suppressor cells (PMN-MDSCs) have been recently identified as the major immune cell type that leads to an immunosuppressive microenvironment in ARID1A-deficient prostate cancer." (PMID 36980292, 2023). "In summary, we suggest that although ARID1A is not frequently mutated and well-studied in prostate cancer, it may be one of the important factors in tumorigenesis of prostate tumors and may act as a potential biomarker for this cancer." (PMID 36035123, 2022). "Consistent with data from analysis of in vivo tumours, knockout of ARID1A in the human prostate cancer DU145 cells significantly promoted growth, increasing cell counts in DU145 ARID1A knockout KO2, KO4 clones and KO pool cells by 68%, 45% and 38% respectively." (PMID 39885328, 2025). "Indeed, cFos, a key component of AP-1, when combined with ARID1A and PTEN, is found to be highly prognostic in a cohort of clinical prostate cancer." (PMID 39885328, 2025). "By overlaying Micro-C signals with RNA-seq signals, we noted that the ARID1A gene, which was reported to be dysregulated in prostate tumors, was lowly expressed in C42B prostate cancer cells while the DISP3 gene was not expressed." (PMID 36544209, 2022).
squamous cell carcinoma (16 papers, 2020 to 2025). A carcinoma arising from squamous epithelial cells. "Both penile tumors (squamous cell carcinoma) exhibited mutations in BRCA1 and FAS, as well as ARID1A, CHEK2, BRCA2, and were Human Papillomavirus (HPV) positive." (PMID 41395625, 2025). "Conversely, the deubiquitinase USP11 has been shown to inhibit squamous cell carcinoma by stabilizing ARID1A protein through its interaction with syndecan‐2 (SDC2)." (PMID 38041544, 2023). "A recent study has identified the E3 ligase TRIM32 as a component of the ubiquitin‐proteasome system that promotes squamous cell carcinoma by facilitating the degradation of ARID1A protein." (PMID 38041544, 2023). "A recent study has reported that promoter hypermethylation plays a role in reducing ARID1A expression, disrupting transcriptional homeostasis and contributing to tumour progression in squamous cell carcinoma." (PMID 38041544, 2023). "ARID1A significantly inhibits the proliferation and progression of squamous cell carcinoma via mediating with SDC2, WNT, Akt and Ras signaling pathways." (PMID 35715413, 2022). "With regards to routine histopathological workup, we identified KRT18 in combination with UCHL1 as potential immunohistochemical markers to differentiate NEC-like IDH2 and NEC-like SMARCA4/ARID1A tumors from adenoid cystic carcinomas, olfactory neuroblastomas and squamous cell carcinomas." (PMID 36443295, 2022). "For example, USP11 can prevent the progression of squamous cell carcinoma by stabilizing ARID1A." (PMID 35359344, 2022). "Targeting Trim32/USP11/ARID1A/SDC2 might be a potential therapeutic strategy for patients with squamous cell carcinoma." (PMID 35715413, 2022). "The NEC-like SMARCA4/ARID1A class (n = 33) mainly consisted of tumors that had been diagnosed as SNUCs, neuroendocrine carcinomas and olfactory neuroblastomas, but also single adenocarcinomas, poorly differentiated carcinomas and squamous cell carcinomas." (PMID 36443295, 2022). "Additionally, ARID1A and ARID2 mutations were more frequently found in males, SMARCA4 was more frequently mutated in patients with adenocarcinoma, and the ARID1B mutation was more frequently found in patients with squamous carcinoma, which were all statistically significant." (PMID 34512623, 2021). "Squamous cell carcinomas (SCCs) are aggressive, and patients with SCCs have low ARID1A (AT-rich interaction domain 1A) expression, resulting in poor prognosis." (PMID 33802079, 2021). "ARID1A interacts with Rb to prevent CDK‐mediated Rb phosphorylation, inhibit E2F transcription factor 1 (E2F1) activity, and subsequently inhibit c‐Myc transcription, revealing a new mechanism of ARID1A in squamous cell carcinoma (SCC)." (PMID 39779467, 2025). "While normal tissue, squamous cell carcinomas and cases from the ACC tumor class were mostly assigned to distinct groups, the differentiation between olfactory neuroblastomas, cases from the NEC-like IDH2 and NEC-like SMARCA4/ARID1A class was less evident." (PMID 36443295, 2022). "Research has found that TRIM32 depletion can inhibit the proliferation, metastasis, and chemotherapy resistance of squamous cell carcinoma (SCC) by stabilizing ARID1A, while USP11 depletion can promote the development of SCC by promoting the degradation of ARID1A." (PMID 35359344, 2022). "Next, n = 116 samples of patients with pure squamous cell carcinoma (n = 68) and mixed urothelial carcinoma with substantial squamous differentiation (n = 48) were analyzed for seven SWI/SNF complex proteins (ARID1A, SMARCA4, SMARCB1, SMARCC1, SMARCC2, SMARCA2 and PBRM1) by immunohistochemistry." (PMID 33227989, 2020).
squamous cell carcinoma (continued). "UCHL1 expression was high in NEC-like IDH2 and NEC-like SMARCA4/ARID1A tumors as well as olfactory neuroblastomas but absent in tumors from the ACC class and squamous cell carcinomas." (PMID 36443295, 2022).